PKD2 (polycystin 2, transient receptor potential cation channel)
Description:
Forms a nonselective cation channel. Can function as a homotetrameric ion channel or can form heteromer with PKD1. Displays distinct function depending on its subcellular localization and regulation by its binding partners. In primary cilium functions as a cation channel, with a preference for monovalent cations over divalent cations that allows K(+), Na(+) and Ca(2+) influx, with low selectivity for Ca(2+). Involved in fluid-flow mechanosensation by the primary cilium in renal epithelium (By similarity). In the endoplasmic reticulum, likely functions as a K(+) channel to facilitate Ca(2+) release (By similarity). The heterotetrameric PKD1/PKD2 channel has higher Ca(2+) permeability than homomeric PKD2 channel and acts as a primarily Ca(2+)-permeable channel. Interacts with and acts as a regulator of a number of other channels, such as TRPV4, TRPC1, IP3R, RYR2, ultimately further affecting intracellular signaling, to modulate intracellular Ca(2+) signaling. Together with TRPV4, forms mechano- and thermosensitive channels in cilium. In cardiomyocytes, PKD2 modulates Ca(2+) release from stimulated RYR2 receptors through direct association (By similarity). Also involved in left-right axis specification via its role in sensing nodal flow; forms a complex with PKD1L1 in cilia to facilitate flow detection in left-right patterning (By similarity). Acts as a regulator of cilium length together with PKD1 (By similarity). Mediates systemic blood pressure and contributes to the myogenic response in cerebral arteries though vasoconstriction (By similarity).
Synonyms: PC2; TRPP2; PKD4; Pc-2; APKD2
Tractability: Small molecule: a structure with a bound ligand is known; it belongs to a druggable protein family. Antibody: UniProt places it where antibodies can reach, with high confidence; its Gene Ontology location is reachable by antibodies, with high confidence; UniProt predicts a signal peptide or a membrane-spanning region; the Human Protein Atlas places it where antibodies can reach. PROTAC: UniProt records ubiquitination sites on it; ubiquitination databases record sites on it.
Target class: Voltage-gated ion channel; Ion channel; Transient receptor potential channel
Gene: Protein-coding gene on chromosome 4 (88,007,629 to 88,077,777, forward strand). Ensembl gene ENSG00000118762.
Subcellular location: Cell projection, cilium membrane; Endoplasmic reticulum membrane; Cell membrane; Basolateral cell membrane; Cytoplasmic vesicle membrane; Golgi apparatus; Vesicle; Secreted, extracellular exosome
Subcellular location (Human Protein Atlas): Endoplasmic reticulum; Plasma membrane; Cytosol; Predicted to be secreted
Pathways (Reactome):
Organelle biogenesis and maintenance: VxPx cargo-targeting to cilium
Gene Ontology:
Molecular function: actinin binding; calcium channel activity; calcium ion binding; calcium-induced calcium release activity; cytoskeletal protein binding; HLH domain binding; identical protein binding; monoatomic cation channel activity; phosphoprotein binding; potassium channel activity; protein binding; protein homodimerization activity; signaling receptor binding; transcription regulator inhibitor activity; transmembrane transporter binding; voltage-gated calcium channel activity; voltage-gated monoatomic cation channel activity; voltage-gated monoatomic ion channel activity; voltage-gated potassium channel activity; voltage-gated sodium channel activity; ATPase binding; outward rectifier potassium channel activity; channel activity; sodium channel activity
Biological process: aorta development; branching involved in ureteric bud morphogenesis; calcium ion transmembrane transport; calcium ion transport; cell surface receptor signaling pathway; cellular response to cAMP; cellular response to fluid shear stress; cellular response to hydrostatic pressure; cellular response to osmotic stress; cilium organization; determination of liver left/right asymmetry; heart development; heart looping; liver development; mesonephric duct development; mesonephric tubule development; metanephric ascending thin limb development; metanephric cortex development; metanephric cortical collecting duct development; metanephric distal tubule development; metanephric mesenchyme development; metanephric part of ureteric bud development; metanephric S-shaped body morphogenesis; metanephric smooth muscle tissue development; negative regulation of G1/S transition of mitotic cell cycle; and 36 more
Cellular component: basal cortex; basal plasma membrane; basolateral plasma membrane; cation channel complex; ciliary basal body; cilium; cytoplasm; cytoplasmic side of endoplasmic reticulum membrane; cytoplasmic vesicle membrane; endoplasmic reticulum; endoplasmic reticulum membrane; extracellular exosome; lamellipodium; lumenal side of endoplasmic reticulum membrane; membrane; migrasome; mitotic spindle; plasma membrane; polycystin complex; vesicle; cell-cell junction; Golgi apparatus; motile cilium; non-motile cilium; ciliary membrane; and 1 more
Genetic constraint (gnomAD): Loss-of-function variants: 32 observed, 62.89 expected, observed/expected ratio (o/e) 0.51, 90% interval 0.38 to 0.68. The upper end of that interval is the gene's LOEUF score, 0.68, which puts it in group 2 of 6, group 1 being the genes least tolerant of losing a copy. Missense variants: 792 observed, 875.21 expected, observed/expected ratio (o/e) 0.9, 90% interval 0.85 to 0.96. Synonymous variants: 350 observed, 343.34 expected, observed/expected ratio (o/e) 1.02, 90% interval 0.93 to 1.11.
Gene-disease validity (ClinGen):
ClinGen rates the evidence that PKD2 causes each of these diseases.
autosomal dominant polycystic kidney disease (autosomal dominant): Definitive. Autosomal dominant form of polycystic kidney disease.
Homologues: Orthologues: chimpanzee PKD2 (99% identical), macaque PKD2 (99% identical), dog PKD2 (95% identical), pig PKD2 (93% identical), rabbit PKD2 (91% identical), mouse Pkd2 (90% identical), guinea pig PKD2 (75% identical), tropical clawed frog pkd2 (71% identical), zebrafish pkd2 (62% identical), Caenorhabditis elegans pkd-2 (26% identical), Drosophila melanogaster Pkd2 (24% identical). Paralogues in human: PKD2L1 (41% identical), PKD2L2 (29% identical), PKD1 (18% identical), PKDREJ (15% identical), PKD1L1 (14% identical), LOXHD1 (13% identical), PKD1L3 (11% identical), DENND5B (10% identical), PKD1L2 (10% identical), DENND5A (10% identical).
Diseases named in the same sentence as PKD2 in open-access papers:
PKD2 is named in the same sentence as 173 diseases in open-access papers, as found by Europe PMC text mining. Sharing a sentence is not in itself a finding about the gene and the disease. The quoted sentences say what the papers report.
autosomal dominant polycystic kidney disease (308 papers, 2006 to 2026). "PKD1 and PKD2 are the most commonly mutated genes in autosomal dominant polycystic kidney disease (ADPKD)." (PMID 41086943, 2025). "Mutations in PKD1 and PKD2 cause autosomal dominant polycystic kidney disease (ADPKD), the most common renal genetic disease, leading to the dysregulation of renal tubules and the development of cystic growth that compromises kidney function." (PMID 40722835, 2025). "Millions of individuals carry pathogenic genetic variants in PKD2 that cause a life-threatening condition called autosomal dominant polycystic kidney disease (ADPKD)." (PMID 40504156, 2025). "PKD1 and PKD2 mutations cause autosomal dominant polycystic kidney disease (ADPKD), often leading to kidney failure." (PMID 40909272, 2025). "Pathogenic variants in PKD1 and PKD2 genes are the leading cause of autosomal dominant polycystic kidney disease (ADPKD), the most common type amongst PKDs, accounting for more than 90% of affected individuals." (PMID 41255498, 2025). "Autosomal-dominant polycystic kidney disease (ADPKD) is a ciliopathy characterized by mutations in PKD1 or PKD2, which drive cystogenesis in renal epithelial cells." (PMID 40814262, 2025). "Autosomal dominant polycystic kidney disease (ADPKD) is an inherited renal disorder that is caused by PKD1 or PKD2 mutations, affects approximately 1 in 1000 live births, and is characterised by the relentless development of renal cysts." (PMID 39747793, 2025). "The medical and biological importance of polycystins is underscored by PKD2 variants associated with autosomal dominant polycystic kidney disease (ADPKD), and this channel’s role in fertility and conferring right-left symmetry in embryonic development." (PMID 38766162, 2024). "Autosomal dominant polycystic kidney disease (ADPKD) is a hereditary kidney disease that is caused by mutation in polycystic kidney disease-1 (PKD1) gene or polycystic kidney disease-2 (PKD2) gene." (PMID 39172111, 2024). "PKD2 was first identified as the pathogenic protein for autosomal dominant polycystic kidney disease (ADPKD) and is widely recognized as an ion channel." (PMID 39451240, 2024). "In autosomal dominant polycystic kidney disease (ADPKD) with germline mutations in a PKD1 or PKD2 gene, innumerable cysts develop from tubules, and renal function deteriorates." (PMID 38474184, 2024). "Mutations of the PKD2 gene in humans are responsible for autosomal dominant polycystic kidney disease (ADPKD)." (PMID 39768206, 2024). "Mutations in PKD1 or PKD2 cause autosomal dominant polycystic kidney disease (ADPKD), which is characterized by continued enlargement of fluid filled cysts within the kidney and other organs." (PMID 39085216, 2024). "PKD2 mutations account for 15% of the autosomal dominant polycystic kidney diseases whereas 85% of the disease is caused by PKD1 mutations." (PMID 37780208, 2023). "PKD2 is a major CKD gene whose mutations cause autosomal-dominant polycystic kidney disease (ADPKD), the most frequent monogenic kidney disease." (PMID 36890159, 2023). "Autosomal dominant polycystic kidney disease (ADPKD) is a common monogenic multisystem disease caused primarily by mutations in the PKD1 gene or PKD2 gene." (PMID 37468838, 2023). "On the contrary, almost all ADPKD patients harbor gene mutations in polycystic kidney disease 1 (PKD1) or polycystic kidney disease 2 (PKD2)." (PMID 35806376, 2022). "Segregation analysis was then performed on the available family members who had features fitting with autosomal dominant polycystic kidney disease and documented the pathogenic PKD2 variant in each subject." (PMID 35627274, 2022). "The proband is also heterozygous for a nonsense PKD2 variant segregating in several maternal autosomal dominant polycystic kidney disease-affected members." (PMID 35627274, 2022).
autosomal dominant polycystic kidney disease (continued). "We report a novel missense mutation, p.Ile424Ser, in the PKD2 gene of an autosomal dominant polycystic kidney disease (ADPKD) patient with multiple liver cysts." (PMID 35447873, 2022). "Autosomal dominant polycystic kidney disease (ADPKD) is caused by mutations in the PKD1 or PKD2 gene which encodes membrane receptor PKD1 and cation channel PKD2, respectively." (PMID 36035467, 2022). "Autosomal dominant polycystic kidney disease (ADPKD) is caused by mutations in PKD1 or PKD2, and is the most common inherited kidney disorder that leads to end-stage renal disease at a prevalence of ∼1:1000." (PMID 34739029, 2021). "Mutations in the PKD1 and PKD2 genes lead to autosomal-dominant polycystic kidney disease (ADPKD), and patients suffering from this disease develop kidney cysts throughout their life." (PMID 34345895, 2021). "Autosomal dominant polycystic kidney disease (ADPKD) is caused by mutations in PKD1 or PKD2 gene and is the most common monogenic kidney disorder." (PMID 33809516, 2021). "Mutations in the PKD2 gene cause autosomal-dominant polycystic kidney disease but the physiological role of polycystin-2, the protein product of PKD2, remains elusive." (PMID 34345895, 2021). "In humans, mutations in TRPP2 (PKD2) result in autosomal dominant polycystic kidney disease (ADPKD), which is the most common monogenic cause of renal failure." (PMID 33378371, 2020). "Multiple ADPKD missense mutations affect the polycystin domain of PKD2 [The Autosomal Dominant Polycystic Kidney Disease Database (PKDB)]." (PMID 33268808, 2020). "For instance, it has been known that the PKD1 and PKD2 genes underlying autosomal dominant polycystic kidney disease (ADPKD) play a role in the male reproductive system." (PMID 32752000, 2020). "In particular, fibrocystin (PKHD1) is involved in autosomal recessive polycystic kidney disease (ARPKD), while polycystin-1 (PKD1) and polycystin-2 (PKD2) are implicated in autosomal dominant polycystic kidney disease (ADPKD)." (PMID 33339422, 2020). "Mutations in the polycystin genes, PKD1 or PKD2, result in Autosomal Dominant Polycystic Kidney Disease (ADPKD)." (PMID 30769894, 2019). "For example, mutations of PKD1 and PKD2 are causal for autosomal dominant polycystic kidney disease, with kidney ECs and tubular cells of patients evidencing deficient calcium and NO responses and increased proliferation." (PMID 31344780, 2019). "Autosomal dominant polycystic kidney disease (ADPKD) is mainly caused by mutations in the PKD1 (~85%) or PKD2 (~15%) gene which, respectively, encode polycystin-1 (PC1) and polycystin-2 (PC2)." (PMID 31341901, 2019). "A recent analysis of mutations in the PKD1 or PKD2 genes leads to ~87% and 13%, respectively, of the cases of autosomal dominant polycystic kidney disease (ADPKD)." (PMID 31207979, 2019). "Mutations in the cation channel PKD2 cause human autosomal dominant polycystic kidney disease but its channel function and gating mechanism are poorly understood." (PMID 29899465, 2018). "Mutations in the corresponding genes, Pkd1 and Pkd2, have been associated with autosomal dominant polycystic kidney disease (ADPKD)." (PMID 29468160, 2018). "Mutations either on the PC1-encoding gene polycystic kidney disease 1 (PKD1) or the PC2-encoding gene polycystic kidney disease 2 (PKD2) cause autosomal dominant polycystic kidney disease (ADPKD), which represents the most common genetic disease." (PMID 30597875, 2018). "Autosomal dominant polycystic kidney disease (ADPKD) is an adult-onset disease characterized by focal cyst development resulting from heterozygous mutations in PKD1 or PKD2." (PMID 29443690, 2018). "Mutations in the polycystin genes, PKD1 or PKD2, results in Autosomal Dominant Polycystic Kidney Disease (ADPKD)." (PMID 29443690, 2018). "Autosomal Dominant Polycystic Kidney Disease (ADPKD) is caused by mutation of PKD1 or PKD2, which encode polycystin 1 and 2, respectively." (PMID 29563577, 2018).
autosomal dominant polycystic kidney disease (continued). "PKD2 has been studied intensively as a cause of the severe genetic disorder autosomal dominant polycystic kidney disease, in which fluid-filled cysts grow within the kidney, and eventually disrupt its function." (PMID 28011630, 2017). "In humans, autosomal dominant polycystic kidney disease (ADPKD) is associated with loss-of-function mutations in genes that encode for either PKD1 or PKD2." (PMID 27348301, 2016). "Autosomal dominant polycystic kidney disease (ADPKD) is caused by mutations in the PKD1 or PKD2 gene." (PMID 26110849, 2015). "Autosomal-dominant polycystic kidney disease arises from inactivating mutations in the genes PKD1 or PKD2, and currently has few treatment options." (PMID 26528438, 2015). "Systemic manifestations of OFD1 mutations include polycystic kidneys that resemble those caused by mutations in the PKD1 or PKD2 genes associated with autosomal dominant polycystic kidney disease (ADPKD)." (PMID 25180832, 2014). "Pkd2 is a gene that, when mutated, causes autosomal dominant polycystic kidney disease and encodes a transmembrane protein localized to primary cilia." (PMID 23351706, 2012). "Autosomal dominant polycystic kidney disease (ADPKD) is a commonly inherited renal disorder caused by defects in the PKD1 or PKD2 genes." (PMID 20169078, 2010). "Although polycystin-1 (PC1), encoded by the Pkd1 gene, and Polycystin-2 (PC2), encoded by the Pkd2 gene, are mutated in autosomal dominant polycystic kidney disease, loss of polycystin function in mice also causes a severe skeletal phenotype." (PMID 21151991, 2010). "These calcium channels are formed by a complex of polycystin 1 and polycystin 2 (PC1 and PC2), encoded by the PKD1 and PKD2 genes, respectively, which cause autosomal dominant polycystic kidney disease (ADPKD) when mutated." (PMID 17357787, 2007). "Dysfunction of Pkd2 causes autosomal dominant polycystic kidney disease." (PMID 41665947, 2026). "Notably, the role of polycystins in primary cilium and kidney development has been largely studied, showing as PKD1 and PKD2 mutations result in the autosomal dominant polycystic kidney disease." (PMID 40282211, 2025). "Autosomal Dominant Polycystic Kidney Disease (ADPKD) is caused by mutations in PKD1 or PKD2 genes, encoding polycystin-1 (PC1) or polycystin-2 (PC2), respectively, characterized by excessive cell proliferation and fluid secretion, resulting in renal cyst formation and growth." (PMID 41465431, 2025). "Here, we analyzed orexin-A levels as well as the incidence of SNPs in the hypocretin neuropeptide precursor (HCRT) and its receptors, HCRTR1 and HCRTR2, in 64 patients affected by autosomal dominant polycystic kidney disease (ADPKD) bearing truncating mutations in the PKD1 or PKD2 genes." (PMID 38892431, 2024). "Another example is polycystin-2 (PKD2), whose mutations are linked to autosomal dominant polycystic kidney diseases characterized by the lifelong formation of fluid-filled cysts originating from parts of the nephron and collecting ducts, leading to renal failure." (PMID 37780208, 2023). "Mutations in PKD1 and PKD2 cause autosomal dominant polycystic kidney disease (ADPKD), a progressive inherited disorder in which the renal tissue is gradually replaced with fluid-filled cysts, giving rise to chronic kidney disease (CKD) and progressive loss of renal function." (PMID 37510333, 2023). "Autosomal dominant polycystic kidney disease is caused by mutations in PKD1 or PKD2 genes." (PMID 37028763, 2023). "Mutations in the polycystin-2 gene (PKD2) lead to autosomal dominant polycystic kidney disease." (PMID 35741008, 2022). "Consistent with the gene dosage effect hypothesis, renal cysts can arise in transgenic murine models overexpressing either PKD1 or PKD2, which are causal genes for autosomal dominant polycystic kidney disease (ADPKD)." (PMID 31979107, 2020).